TNF (tumor necrosis factor)
Diseases named in the same sentence as TNF in open-access papers (continued):
Sharing a sentence is not in itself a finding about the gene and the disease.
periodontitis (continued). "Also, the mean levels of TNF-α and IL-1β in the saliva and GCF of patients with periodontitis were significantly higher than in patients with gingivitis." (PMID 40265034, 2025). "To test this, we compared the expression of OPG and RANKL in GFs from healthy individuals and patients with periodontitis infected with P. gingivalis in the presence or absence of TNF." (PMID 41315835, 2025). "Physical training resulted in a reduced levels of IL-1β, IL-6, TNF-α C-reactive protein and LPO and an increase in the levels of IL-10 in rats with periodontitis (p<0.05); a reduction in the inflammatory infiltrate and decreased fiber degradation was identified in histological analysis." (PMID 38843156, 2024). "In another induced periodontitis in a diabetic rat experiment, Cu reduced the infiltration of PMN and monocytes, the degradation of periodontal collagen fibers—and decreased IL-1β, IL-6, TNF-α MMP-9 and MMP-2, MMP-8 levels." (PMID 38793109, 2024). "Also, it decreased the serum expressions of TNFα and IL-2 and the tissue expression of MMP-2 and -9 in the periodontitis-induced model (p < 0.05)." (PMID 37378834, 2024). "Interestingly, higher levels of all the M1 markers STAT1 (r = .75; p < 0.0001), miR‐155 (r = .8; p < 0.0001), TNF‐α (r = .75; p < 0.0001), and CXCL10 (r = .62; p < 0.001) correlated with PPD in the periodontitis group." (PMID 39436204, 2024). "The serum levels of TNF-α and IL-1β, key proinflammatory cytokines, were highest in the group of rats induced with periodontitis without treatment, confirming the presence of active inflammation." (PMID 39539670, 2024). "A hypomethylation of signal transducers and activators of transcription 5 (STAT5) promoter and prostaglandin-endoperoxide synthase 2 (PTGS2) promoter, increased methylation at two CpG sites of TNF-α and TLR2 gene in gingival tissues from chronic periodontitis patients has been reported." (PMID 38130504, 2024). "There is no study in humans on the effects of anti-TNFα therapy on periapical lesions (chronic apical periodontitis)." (PMID 38256582, 2024). "Additionally, a study on Curcuma longa (turmeric) revealed its efficacy in reducing TNF-α levels and inhibiting matrix metalloproteinase (MMP) activity, which plays a critical role in tissue destruction during periodontitis." (PMID 39539670, 2024). "This strip simultaneously detects three periodontitis biomarkers: MMP-8, IL-1β, and TNF-α." (PMID 39554809, 2024). "While arthritis had no influence on the alveolar bone resorption in periodontitis, arthritic mice exposed to Porphyromonas gingivalis exhibited higher TNF and IL-17 levels and demonstrated more joint damage than control mice." (PMID 39253090, 2024). "Notably, studies have revealed elevated levels of Prostaglandin E2 (PGE2), TNF-α, and IL-1β and functional impairment of polymorphonuclear leukocytes (PMNs) in T1DM individuals, presenting with gingivitis or periodontitis." (PMID 39301048, 2024). "In the absence of systemic diseases, an increase in TNF‐α levels in both fluids was demonstrated in chronic periodontitis compared to normal healthy patients." (PMID 39494478, 2024). "Interestingly, various studies demonstrated TNF‐α‐induced CXCL10 synergistically contribute to the onset and progression of periodontitis." (PMID 39436204, 2024). "Similarly, in our study, we find that NAC‐S2 treatment significantly suppresses the mRNA expression levels of TNF, IL6, and IL‐1β in gingival tissues of periodontitis mice, indicating the protecting role of NAC‐S2 in periodontitis." (PMID 37647428, 2023). "While in the established periodontitis mouse model, NAC‐S2 administration significantly decreases CEJ to ABC distance and suppresses the expression levels of pro‐inflammatory cytokines including TNF, IL‐6, and IL‐1β." (PMID 37647428, 2023).
periodontitis (continued). "Positive staining of TNF-α in the periodontal tissue was discovered in the gingiva of the periodontal region of mice with periodontitis 14 days after ligation compared to non-ligation control tissue." (PMID 37232780, 2023). "Unlike the current results, Varghese et al37 reported a statistically non-significant correlation between TNF-α and periodontitis parameters." (PMID 36794778, 2023). "In the progression of periodontitis in human, NF-κB can be activated by LPS-induced Toll-like receptor 4 (TLR4) activation, which activates gene expression of multiple proinflammatory cytokines, such as IL-1, IL-6, and TNF-α." (PMID 36846719, 2023). "One of the primary virulence factors of periodontitis, Pg-LPS, targets TLR4, which activates the NF-kB signaling pathway and triggers the secretion of inflammatory cytokines such as TNFα, IL-6, and chemokines, recruiting monocytes/macrophages to the site of infection." (PMID 38249288, 2023). "Furthermore, higher IL-1β levels in GCF and similar levels of TNF-α have been demonstrated in patients with OSA and periodontitis." (PMID 36967976, 2023). "Among them, the genus Lachnospiraceae UCG-008 is positively correlated to the release of inflammatory factors such as IL-6, HS-CRP, and TNF-α, indicating that reducing the numbers of Lachnospiraceae UCG-008 is beneficial for controlling inflammation and can function in controlling periodontitis." (PMID 37305424, 2023). "The objective of this study is to assess whether the interaction of baseline serum levels of TNF-α, hs-CRP, ICAM-1, VCAM-1, and adiponectin leads to periodontitis." (PMID 37371602, 2023). "Considering this, the objective of the present study is to assess whether the interaction of baseline serum levels of TNF-α, hs-CRP, ICAM-1, VCAM-1, and adiponectin leads to periodontitis among overweight/obese individuals." (PMID 37371602, 2023). "The presence of gram-negative bacteria and lipopolysaccharide (LPS) by inducing Tumor necrosis factor-alpha (TNF-α), enhances the risk of necroptosis in periodontitis." (PMID 37266108, 2023). "Second, there is still limited evidence of the therapeutic efficacy of TNF inhibitors in patients diagnosed with periodontitis without other comorbidities." (PMID 36845132, 2023). "In the PBS-treated mice, TNF-α mRNA expression was significantly upregulated in the periodontitis-induced (ligated) area compared with that in the nonligated area (p = 0.01)." (PMID 36983482, 2023). "As expected, the mRNA levels of TNF, IL‐6, and IL‐1β dramatically increased in periodontitis mice as compared with control NT mice, while NAC‐S2 treatment significantly suppressed their expression levels in periodontitis mice." (PMID 37647428, 2023). "This is because nicotine induces harmful effects on systemic health, reducing the activity of the immune system and increasing the production of pro-inflammatory cytokine interleukins (IL)-1β and tumor necrosis factor-alpha (TNF-α), thereby increasing the severity of periodontitis." (PMID 37109642, 2023). "In conclusion, IL-17 and TNF-α are closely related to periodontitis, and MAIT cells that can secrete these cytokines might affect the course of periodontitis." (PMID 36896188, 2023). "In periodontitis rats with T1DM, TNF-α could induce increased expression of sclerotin and RANKL in alveolar osteocytes, leading to further alveolar bone resorption and bone loss." (PMID 37664859, 2023). "Furthermore, DEGs in the diabetic periodontitis vs. resveratrol+diabetic periodontitis group were mainly attributed to ferroptosis, HIF-1 signaling, and TNF signaling." (PMID 37432277, 2023). "Some studies have found that smoking periodontitis patients showed elevated levels of proinflammatory cytokines, such as IL-1β and TNF-α, compared with nonsmoking periodontitis patients." (PMID 36726081, 2023). "However, periodontitis also triggers systemic inflammation, indicated by an increased level of C-reactive protein (CRP), TNFα, IL-1β, and IL-6 in the serum of patients." (PMID 35874771, 2022).
periodontitis (continued). "In addition, like TNFα, VEGF has been shown to be increased in periodontitis, indicating a possibly proinflammatory and destructive role in periodontal diseases." (PMID 34405311, 2022). "While anti-Sema4D-mAb downmodulated the bone-resorption induced in mouse periodontitis, it neither affected local production of TNF-α and RANKL nor systemic skeletal bone remodeling." (PMID 35628440, 2022). "Periodontitis patients have been shown to have elevated blood levels of pro-inflammatory markers, such as C reactive protein (CRP), fibrinogen, IL-6, interleukin-1 (IL-1), and TNF-α." (PMID 36015357, 2022). "Analysis of TNF-α levels in this study showed a significant correlation between TNF-α concentrations and the incidence of periodontitis in type 2 DM patients with and without periodontitis." (PMID 35016229, 2022). "Based on the results of this study, it can be concluded that there was a significant increase in the expression of TNF-α and TGF-β1 in periodontitis-induced Wistar rats with SRP treatment and VCO gel administration, which is a marker of periodontal tissue regeneration." (PMID 35178093, 2022). "Moreover, immunohistochemical staining demonstrated expression of HDAC1 by CD3- and TNF-α positive cells, indicating that such cells may be important additional targets to suppress inflammation, suggesting that HDACs modification may be involved in periodontitis pathogenesis." (PMID 36291079, 2022). "There was a correlation between the concentration of TNF-α and the incidence of periodontitis in patients with type 2 DM with and without periodontitis." (PMID 35016229, 2022). "In addition, IL-17A can also act synergistically with IL-1 and TNF-α to induce gingival fibroblasts to produce MMP-1 and MMP-3, which plays an important role in the tissue destruction in periodontitis." (PMID 35371044, 2022). "Notably, circulating inflammatory mediators such as TNF-α, IL-6 and CPR serve as the link between systemic chronic inflammatory diseases and chronic periodontitis, and better early diagnosis of periodontitis by these inflammatory biomarkers." (PMID 36570162, 2022). "It is evident that TNF-α, sTNF-R1, and sTNF-R2 are included in the GCF; however, the details of these are unclear, except for the finding that the ratios of sTNF-R2/R1 in GCF significantly increase after periodontitis treatment." (PMID 35200250, 2022). "This periodontitis-related bacterium induces oral epithelial cells to express inflammatory mediators (interleukin-6 (IL-6), IL-8, tumor necrosis factor-α (TNF-α), prostaglandin E2, and cyclooxygenase-2) without requiring direct contact with these cells." (PMID 35695679, 2022). "These diseases lead to an increase in the salivary IL-6 and TNF-α levels of pregnant women compared with pregnant women without gingivitis and periodontitis." (PMID 35877392, 2022). "The “strict” periodontitis subgroup produced median levels of SOST (140.00 pg), WNT-5a (2.4 pg) and TNF-α (44.7 pg) compared with the “strict” healthy group who exhibited levels of SOST (78.9 pg), WNT-5a (1.29 pg) and TNF-α (27.3 pg)." (PMID 35453967, 2022). "TNF‐α is one of the most important pro‐inflammatory cytokines that are produced by macrophages and T helper 1 (TH1) cells and plays crucial roles in the pathogenesis of periodontitis." (PMID 34719112, 2021). "We observed increased secretion of TNF-α in OBMCs from periodontitis patients with and without IL-2 or IFN-γ treatment." (PMID 33672708, 2021). "As found in the present study, in T2DM patients with periodontitis, statins treatment reduced pro-inflammatory factors IFN-γ, IL-1β, IL-2, IL-6, IL-7, IL-21 and TNF-α levels in GCF, and enhanced anti-inflammatory factors IL-4 and IL-5 levels through the anti-inflammation and anti-oxidation effects." (PMID 33417619, 2021).
periodontitis (continued). "Serum reactive oxygen species, interleukin (IL)-1, IL-6, tumor necrosis factor (TNF)-α, and CRP have been found to be elevated in the bloodstream of patients with established T2DM and may play an important role in tissue breakdown in periodontitis." (PMID 33924022, 2021). "Furthermore, the interaction of NLRP3+ macrophages and structural cells through TNF-TNFRSF1A and CXCR3_CCRL19 offered us a hint of the biological function of NLRP3+ macrophages in periodontitis." (PMID 34566966, 2021). "TNF-α level in PISF in patients with implants reached 5.71 ± 1.94 pg/mL and was markedly higher compared to subjects with healthy periodontium (p = 0.003) and patients with mild periodontitis (p = 0.010)." (PMID 33726736, 2021). "Additionally, in this study, after the treatment of periodontitis, a decrease in the concentration of interferon gamma (INF-γ), IL-17A, TNF-α, and IL-6 in the blood was demonstrated [49••]." (PMID 33961166, 2021). "Further investigation also confirmed the anti‐inflammatory effects of BBR in periodontitis, as it has been shown that following treatment with BBR, the expression levels of pro‐inflammatory cytokines including TNF‐α, IL‐1β, and RANKL markedly downregulated in rat with periodontitis." (PMID 34719112, 2021). "Indirectly, these cells can also induce the amplification of the pro-inflammatory cytokines (IL-1, IL-6, IL-12, IL-17, IL-18, IL-21, TNF-α, and IFN-γ), which are known to be found in periodontitis and to induce osteoclastogenesis via the RANKL–RANK–OPG pathway." (PMID 33143068, 2020). "In the present study, TNF-α levels were significantly decreased in GCF of deep sites in both periodontitis groups, but they did not change in moderate sites." (PMID 33218047, 2020). "The study demonstrated that severe chronic periodontitis was associated with increased serum hs-CRP, but not with any significant elevation of TNF- α or CRP." (PMID 31336777, 2019). "TNF-α has been shown to upregulate sclerostin expression in MLO-Y4 cells; consistent with this finding, the use of a TNF-α antagonist was able to diminish RANKL and sclerostin expression in the osteocytes of diabetic rats with periodontitis." (PMID 31341915, 2019). "Moreover, serum LDLC level well predicted periodontal TNF-α level, suggesting a playing role of LDLC in the partially suppressed cytokine response to periodontitis in overweight individuals." (PMID 30719451, 2019). "IL-2, IFN-γ, TNF and IL-33 exhibited an approximately two-fold increase in RA subjects without periodontitis compared to matched controls." (PMID 31182740, 2019). "Concordantly with these studies performed in vitro, in periodontitis tissue samples, an increase in mRNA of IL-1β, IL-6, IL8, and TNF-α, regulated upon activation normal T cell expressed and secreted (RANTES) and monocyte chemotactic protein-1 (MCP-1), was observed, compared to healthy gingiva." (PMID 31049022, 2019). "The TNF blockers used for the treatment of patients with RA resulted in significant reduction of biochemical markers of PD including IL-1β and IL-8 in the GCF of patients with established periodontitis." (PMID 31540277, 2019). "It is determined that the interindividual differences have been observed in TNF-α production by peripheral blood mononuclear cells or oral leukocytes, isolated from individuals with and without periodontitis." (PMID 29449347, 2018). "TNF-α was not detectable in our minipig model of periodontitis, but the ELISA demonstrated that local icariin significantly decreased IL-1β expression, which indicates that icariin regulated inflammatory and immune reactions in periodontitis." (PMID 29895944, 2018). "In periodontitis, microbial pathogens increase inflammatory infiltrate, that is, T-cells, B-cells, macrophages, and neutrophils with concomitant increase in inflammatory cytokines like IL-1, IL-11, IL-6, TNF-β, TNF-α, TGF-β, kinins, and thrombin." (PMID 29670909, 2018).
periodontitis (continued). "As both macrophages and Th1 cells can stimulate the formation and activity of bone resorbing osteoclasts through TNF-α and INF-γ production, the axis CCL3/CCR1/CCR5 might be relevant for periodontitis pathogenesis." (PMID 29163477, 2017). "Our study suggests that TNF-α might mediate osteocytic RANKL and the sclerostin expression in type 1 diabetes with periodontitis." (PMID 29240821, 2017). "Therefore, the objective of this study was to determine the effect of infliximab (IFX), a TNF-α antagonist, on osteocytic RANKL and sclerostin expression in STZ-induced type 1 diabetes rats with periodontitis." (PMID 29240821, 2017). "In NDM subjects, the concentration of TNF-α in the nonperiodontitis group was significantly higher than in the mild periodontitis group (P = 0.002) and the moderate periodontitis group (P < 0.001)." (PMID 29109737, 2017). "Cluster 6 contained 34 genes with strong positive correlations with MMP9 and CTSK in both healthy and periodontitis tissues, and a negative correlation with TNFα in periodontitis." (PMID 27486459, 2016). "The current study revealed that the levels of Th1 cytokines IFNG and IL12 did not change between healthy and periodontitis-affected gingival samples while that of TNF slightly increased in periodontitis." (PMID 27531006, 2016). "Elevated numbers of macrophages and pro-inflammatory cytokines interleukin (IL)-1, tumour necrosis factor alpha (TNF-α), macrophage inflammatory protein 1-alpha (MIP-1α) and IL-8 secreted by macrophages have been detected in gingival tissue biopsies from chronic periodontitis patients." (PMID 27383471, 2016). "Tumor necrosis factor-α (TNF-α), which is present at high levels in both gingival crevicular fluid and periodontal tissues of diseased sites, is involved in the pathogenesis of periodontitis." (PMID 27529224, 2016). "Some authors have shown higher serum IL-6 and TNF-α levels in healthy smokers when compared to the healthy nonsmokers and higher TNF-α levels in patients with periodontitis in comparison to the healthy controls." (PMID 25858079, 2015). "Interleukin-6 correlates with the presence of periodontitis; however, the TNF-α levels do not differ between periodontitis cases and healthy subjects." (PMID 25884025, 2015). "The aim of the present study was to quantify the total levels of interleukin (IL)-1α, -1β, -6, -10 and tumour necrosis factor (TNF)-α in gingival crevicular fluid (GCF) of chronic periodontitis patients prior to and following nonsurgical periodontal therapy." (PMID 24944641, 2014). "Thus, IL-1β, TNF-α, and PGE2 will all activate osteoclast activity, MMP secretion, and alveolar bone resorption in chronic periodontitis." (PMID 24944840, 2014). "The present study was performed to determine whether presence of periodontitis and periodontal therapy could influence the serum levels of CRP & TNF-α in cardiovascular disease patients." (PMID 24198887, 2013). "Therefore, further studies should focus on the relationship between periodontitis, elevated CRP & TNF-α levels and the effect of periodontal therapy on serum inflammatory markers concentration." (PMID 24198887, 2013). "Venlafaxine (10 mg/kg) failed to reduce the TNF- α as well as the iNOS immune-staining in the periodontium of rats submitted to experimental periodontitis (respectively)." (PMID 20546603, 2010). "The ability of IL-10 to modulate key pro-inflammatory cytokines such as IL-1β, TNF-α, and IL-6, along with its interplay with IL-17 signaling and its regulatory effects on osteoclast differentiation and ABL, points to its multifaceted role in the pathophysiology of periodontitis." (PMID 41289041, 2025). "Furthermore, a positive association has been established between USP5 overexpression and enhanced production of pro‐inflammatory cytokines, including TNF‐α, IL‐6 and IL‐1β in PDLSCs, suggesting that USP5 triggered inflammation and consequently aggravated periodontitis." (PMID 39626954, 2025).